LEP (leptin)
Diseases named in the same sentence as LEP in open-access papers (continued):
Sharing a sentence is not in itself a finding about the gene and the disease.
breast cancer (continued). "Upon leptin exposure, breast cancer cells exhibit increased proliferation, reduced apoptosis, and enhanced angiogenesis to support greater tumor growth." (PMID 34389732, 2021). "We also found that the methylation level of the LEP promoter was higher in breast cancer tissue than in normal tissue." (PMID 34414945, 2021). "LDFI peptide significantly reduced exosome secretion in both MCF-7 and MDA-MB-231 breast cancer cells, demonstrating the leptin/leptin receptor/Hsp90 axis as an important regulator of exosome generation in mammary carcinoma cells." (PMID 34356668, 2021). "We also noted that breast cancer patients with estrogen receptor positive breast cancer exhibited better overall survival with higher miR-205, low Med1 and low leptin expression levels." (PMID 34389732, 2021). "Leptin addition also activated the SDF-1/CXCR4 axis to promote invasive behavior in the breast cancer cell lines MCF-7 and SK-BR-3." (PMID 33799880, 2021). "In MCF-7 (ER-positive) breast cancer cells, leptin increased proliferation through a STAT3-dependent pathway." (PMID 34944905, 2021). "In the present study, elevated FAO and ATP generation appears to occur concomitantly, strongly suggesting a close interrelation between these two outcomes in leptin‐stimulated breast cancer cells." (PMID 33226729, 2021). "Adding to the discrepancies, a study of leptin immunostaining of breast cancer tissues reported more recurrences and poorer survival with low or negative detection." (PMID 34876619, 2021). "Data demonstrated in the present study reveal a novel mechanism by which leptin increases the supply of fatty acid for energetic generation and other metabolic needs of breast cancer cells." (PMID 33226729, 2021). "Leptin, as a mediator of tumor-stromal interactions, can affect the activity of breast cancer stem cells (BCSC) that play a key role in tumor progression." (PMID 34356668, 2021). "The results of this study indicated that IONP-LPrA2 represents an efficient delivery system for the leptin antagonist LPrA2 to target and treat breast cancer; furthermore, it acts as an adjuvant when administered with chemotherapeutics." (PMID 34356668, 2021). "Oncomine analysis of cancer versus normal tissues showed that LEP was downregulated in breast cancer to a greater extent than in other cancers." (PMID 34414945, 2021). "As expected, breast cancer cells exposed with leptin showed increased clonogenicity and soft-agar colonies even in the presence of tamoxifen treatment." (PMID 34389732, 2021). "We next asked if fatty acid can be used as a fuel source for leptin‐stimulated ATP production in breast cancer cells." (PMID 33226729, 2021). "A combination of BMI, leptin levels, leptin/adiponectin ratio, and CA 15-3 levels as biomarkers for breast cancer has shown high reliability." (PMID 34730888, 2021). "Paraoxonase 1 (PON1), leptin (LEP) and leptin receptor (LEPR) genes are good example of a GWAS-identified locus that has been implicated in development of breast cancer." (PMID 34452542, 2021). "Chromatin immunoprecipitation analysis showed that leptin induced the recruitment of Med1 on ERE region of ER promoter while co-treatment of breast cancer cells with AG825, AG1478, or PD98059 along with leptin resulted in significant reduction in Med1 binding." (PMID 34389732, 2021). "In summary, we decided to evaluate the impact of LEP and LEPR genes polymorphisms on the development of breast cancer in women from the Greater Poland region." (PMID 33864589, 2021). "In a 4T1 mouse mammary cancer model, leptin increased the expression of VEGF, thereby promoting angiogenesis leading to breast cancer progression." (PMID 34944905, 2021). "Our preliminary study also suggests that treatment with leptin leads to a significant increase in cellular amino acid levels in breast cancer cells (unpublished data) as a result of elevated uptake or de novo synthesis of amino acids." (PMID 33535537, 2021).
breast cancer (continued). "These adipocyte secretory factors (IL-6, TNF-α and leptin) were identified in acquired breast cancer drug resistance." (PMID 34812105, 2021). "The leptin induced EMT in breast cancer cells was reported to involve an upregulation of IL-8 and pyruvate kinase M2 (PKM2) via PI3K/Akt signaling." (PMID 34588926, 2021). "Herein, leptin induced significant increase in fatty acid oxidation‐dependent ATP production in estrogen receptor‐positive breast cancer cells." (PMID 33226729, 2021). "It was able to inhibit leptin-dependent growth of human breast cancer xenografts by approximately 50% when administered intraperitoneally or subcutaneously at a 0.1 mg/kg/day dose." (PMID 34356668, 2021). "On the contrary, our finding showed that leptin was negatively correlated with neural invasion in breast cancer patients." (PMID 34970222, 2021). "who reported on a novel leptin antagonist peptide which was found to inhibit breast cancer growth in vitro and in vivo." (PMID 33859943, 2021). "A recent review has discussed the roles of BMAds (and leptin, adiponectin, and Sam68 specifically) in bone metastasis from breast cancer." (PMID 33498240, 2021). "Leptin enhances the aromatase expression in the MCF-7 (ER-positive) cell line and can activate the ER in the same cell line, implying that leptin can induce breast cancer progression through the previously outlined effects by estrogens." (PMID 34944905, 2021). "In this study, serum leptin and leptin receptor (ObR) levels were investigated in 58 cats with mammary carcinoma and compared with those of healthy animals, as were the expression levels of leptin and ObR in tumor tissues." (PMID 33644151, 2021). "The Free Leptin Index (FLI) was determined in the serum samples of cats with mammary carcinomas and compared with healthy animals." (PMID 33644151, 2021). "Although overweight is a common condition in cat, the role of leptin and its receptor in feline mammary carcinoma remains unsettled." (PMID 33644151, 2021). "Oncomine analysis identified co-expression of LEP with a large cluster of 19,273 genes across 11 breast carcinomas." (PMID 34414945, 2021). "Altogether, these findings provide support for the crosstalk between the leptin/ObR axis and tumor immunoediting mechanisms, contributing to an immunosuppressive status in cats with mammary carcinoma." (PMID 33644151, 2021). "More recently, we also reported that an enhanced production of leptin from anastrozole-resistant MCF-7 breast cancer cells impacts macrophage behavior within the TME." (PMID 32727138, 2020). "Studies using both in vivo and in vitro experimental models have extensively demonstrated the involvement of leptin in many aspects of breast cancer biology starting from the early stages of primary tumour to metastatic progression." (PMID 32033341, 2020). "For example, the relevance of leptin signalling in breast cancer development differs according to the ethnicity of patients." (PMID 33173414, 2020). "As an example, it was shown that leptin increases IL-18 expression and secretion in TAMs, leading to increased migration and invasion of breast cancer cells." (PMID 32824322, 2020). "Leptin can enhance the secretion of soluble intercellular adhesion molecule (sICAM)-1 by breast cancer cells to induce osteoclastogenesis and accelerate bone erosion." (PMID 33123472, 2020). "Breast cancer patients are characterized by high serum leptin concentrations as well as increased leptin receptor expression especially in higher pathological grade tumor tissues and patients who develop resistance to anti-cancer treatments." (PMID 32257945, 2020). "The interaction of leptin with cytokines can also influence breast cancer progression: leptin acts on both tumour cells and tumour stroma to secrete inflammatory cytokines such as IL-1, IL-6, TNF-α, and growth factors." (PMID 32033341, 2020).
breast cancer (continued). "ASCs-derived leptin promoted tumor growth and metastasis of estrogen receptor-positive breast cancer by upregulating PAI-1 and MMP-2." (PMID 33371368, 2020). "Mouse mammary tumor virus (MMTV)-Wnt-1 transgenic mice, which develop spontaneous breast cancer under a diet-induced obesity regimen, present increased leptin production, upregulated EMT gene expression, and reduced survival." (PMID 33123472, 2020). "First, leptin peptide receptor antagonist is reported to suppress leptin-induced chemoresistances in breast cancer cells." (PMID 33123472, 2020). "A meta-analysis study revealed that serum leptin profile plays an important role in pathogenesis of breast cancer." (PMID 33511131, 2020). "A decrease in adiponectin concentration and a corresponding increase in concentration of leptin, resistin, visfatin, IL-6, IL-8, and TNF-α are linked with progression of breast cancer." (PMID 33511131, 2020). "The adipocyte-derived leptin, whose synthesis and plasma levels increase in parallel to total adipose tissue mass, has an important role in promoting breast cancer progression." (PMID 32260113, 2020). "Expression of leptin and its receptors have been reported in different types of cells and tissues such as adipose, liver, lung, ovary and breast cancer." (PMID 32133259, 2020). "Decreased levels of adiponectin are associated with higher body mass indices and higher fat percentages, whereas the ratio of adiponectin to leptin is a key determinant of the effect of adipokines on the pathological process of breast cancer." (PMID 33108715, 2020). "Breast cancer progression is promoted further by leptin stimulated STAT3 mediated FAO in CD8+ T effector cells." (PMID 32331320, 2020). "Leptin and adiponectin have been shown to have contrary functions on breast cancer progression, leptin displaying tumor-promoting and adiponectin tumor-suppressive roles, f.i. through cell proliferation." (PMID 33490070, 2020). "For example, adipocyte-derived leptin and IL-1β increase breast cancer cell colonization and migration to the adipose tissue adipocytes of the skeleton." (PMID 32092997, 2020). "In the stroma of breast cancer, adipocytes, along with fibroblasts, macrophages, and cancer cells produce adipokines such as leptin, adiponectin, autotoxin, and IL-6." (PMID 32033341, 2020). "In the present study, we report a novel mechanism by which leptin signaling pathway impacts AI resistance, contributing to enhanced crosstalk between anastrozole-resistant breast cancer cells and macrophages within the tumor microenvironment." (PMID 32260113, 2020). "Average leptin mRNA expression (0.6713) was the highest in breast cancer compared to other cancer types analyzed." (PMID 33019728, 2020). "Leptin and insulin increase Sam68 expression in breast cancer cell lines, with an increase in its tyrosine phosphorylation." (PMID 32033341, 2020). "In an in vitro and in vivo experimental approach, rosiglitazone antagonizes the proliferative effects exerted by leptin in breast cancer cells and abrogates the leptin-induced tumor growth in nude mice implanted with MCF-7 cells." (PMID 32937951, 2020). "We subsequently investigated leptin as a therapeutic target for preventing mammary cancer metastasis in dogs and identified it as an endogenous LAMP2a activator by modulating its stability and promoting multimerization." (PMID 33255835, 2020). "High concentrations of leptin and resistin favor cancer cell proliferation and have recently been reported to be casual factors in acquired breast cancer treatment resistance." (PMID 32257945, 2020). "A moderate negative correlation was observed between leptin and adiponectin (r = −0.3539; p = 0.053); adiponectin is known to exert potent anti-tumour activities, whereas leptin exhibits pro-tumorigenic properties in breast cancer." (PMID 33213024, 2020). "Consistent with the results of a previous study, inhibition of miR-34a by external leptin was confirmed in different breast cancer cells." (PMID 33371368, 2020).
breast cancer (continued). "This is highly dependent on the Notch, IL-1, and leptin cross-talk outcome (NILCO) in breast cancer." (PMID 33123472, 2020). "Enhanced expression of leptin and leptin receptors has been reported in breast cancer in comparison to normal breast tissue and was significantly related to distant metastasis." (PMID 32573960, 2020). "For instance, there is a potential cross-talk between leptin and metastasis-associated protein 1 (MTA1)/Wnt signaling in EMT of breast cancer cell lines." (PMID 33123472, 2020). "Leptin is believed to be involved in the growth and invasion of breast cancer cells by stimulating the conversion of aromatisable androgens (androstenedione and dehydroepiandrosterone) to oestradiol." (PMID 32512860, 2020). "We also investigated adiponectin, an adipokine that is released in breast adipose tissue and appears to counteract leptin in the progression of breast cancer." (PMID 33213024, 2020). "Bone metastases from breast cancer express components of the leptin/LEPR/KHDRBS1 axis in an expression pattern that partly follows that of the primary tumour but also exhibits peculiarities." (PMID 33213024, 2020). "The results of this study demonstrate that increased leptin expression promoted bone metastasis of breast cancer cells." (PMID 32836215, 2020). "The adipocyte-derived leptin, a crucial adipokine in fueling breast cancer progression, promotes EMT via the upregulation of PKM2 expression and the activation of PI3K/AKT signaling pathway." (PMID 32793598, 2020). "We therefore explored the role of the SDF-1/CXCR4 axis in leptin-mediated bone metastasis of breast cancer cells." (PMID 32836215, 2020). "In this study, we found that leptin downregulated expression of the epithelial marker E-cadherin and upregulated expression of the mesenchymal marker vimentin in breast cancer cells." (PMID 32836215, 2020). "Leptin induced the metastasis of breast cancer cells by activating the SDF-1/CXCR4 axis, and upregulation of CXCR4 contributed to bone metastasis and poor survival in breast cancer patients." (PMID 32836215, 2020). "Leptin expression in normal breast tissue adjacent to ductal carcinoma and its absence in the breast tissue of healthy adults suggests that leptin is involved in the early stages of breast cancer tumorigenesis." (PMID 32033341, 2020). "Accordingly, targeting this fatty acid β-oxidation pathway inhibits leptin-induced breast cancer stemness." (PMID 33123472, 2020). "Leptin, an adipokine secreted by adipose tissue, promotes tumour invasiveness and growth of breast cancer cells through autocrine and paracrine loops." (PMID 33213024, 2020). "The roles of both leptin and leptin receptor (ObR) in numerous pathophysiological conditions including mammary tumor (MT) development have been reported." (PMID 32133259, 2020). "obASCs promote estrogen receptor positive breast cancer (ER+BC) through leptin upregulation of ERα and aromatase." (PMID 32326381, 2020). "In conclusion, we demonstrate in this study that leptin was an important promoter of bone metastasis and influenced prognosis in breast cancer patients." (PMID 32836215, 2020). "These adipocytokines affect cancer cell biology, and, for breast cancer, IL-1β overexpression in addition to leptin is reported to induce cancer cell colonization in BM." (PMID 32674405, 2020). "Following the analysis of FGFR1 mRNA and leptin mRNA in primary breast cancer, we analyzed the relationship of FGFR1 mRNA and leptin mRNA in normal breast tissue, breast tumor-adjacent tissue, and tissue from metastatic breast cancer." (PMID 33019728, 2020). "Some researchers identified the expression of LEP in mouse serum exosomes; in breast cancer, LEP enhances intercellular signal communication by promoting exocrine secretion." (PMID 33169793, 2020). "In MCF-7 and MCF10AT1 breast cancer cells, leptin downregulates CDH1 expression and upregulates SNAI2 expression through an autocrine mechanism that involves the expression and secretion of TGFB1." (PMID 33334030, 2020).
breast cancer (continued). "Leptin has largely been reported to have a tumor growth-promoting influence in rodent models of breast cancer." (PMID 33604295, 2020). "Leptin-induced PAI-1 provides evidence for the critical roles of tumor microenvironment in breast cancer malignant evolution by affecting PAI-1 expression." (PMID 33371368, 2020). "As the bulk supporting tissue of breast cancer, IL-6 and leptin release by white adipose tissue has been correlated with paracrine activation of STAT3 (canonical) thereby driving metastatic process." (PMID 32331320, 2020). "Our analyses showed a significantly higher concentration of leptin as well as a lower concentration of adiponectin with increasing BMI in breast cancer subjects." (PMID 32512860, 2020). "Treatment of MCF-7 and MDA-MB-231 breast cancer cells with leptin led to increased expression of VEGFA." (PMID 32318345, 2020). "In the case of breast cancer more specifically, the mechanisms that have been purposed as key factors in this interaction include leptin, adipose tissue inflammation, insulin and insulin growth factor(IGF-1) and sex hormones." (PMID 33371214, 2020). "Compared to the control group, coadministration of SDF-1 significantly increased leptin-induced invasiveness in breast cancer cells." (PMID 32836215, 2020). "To summarize the results from a clinical perspective, we described that leptin/OBR is tightly related to PAI-1 expression in breast cancer, which is novel evidence reflecting cytokine-mediated communication between adipocytes and breast cancer cells." (PMID 33371368, 2020). "Of the 29 types of primary cancer, the average FGFR1 mRNA expression in breast cancer is the sixth highest overall (2.8852), and third highest among cancers where a significant relationship between leptin mRNA and FGFR1 mRNA was observed." (PMID 33019728, 2020). "Mechanism research reveals that breast cancer cells are recruited to the human bone tissue by leptin and IL-1β derived from BMAs." (PMID 33123472, 2020). "In both ER+ and ER− breast cancers, there was a positive association between FGFR1 mRNA, and LepR mRNA, although ER- tumors had significantly higher leptin mRNA compared to ER+ tumors." (PMID 33019728, 2020). "Studies have suggested that leptin levels can be a good predictor for breast cancer diagnosis, prognosis and survival." (PMID 33371214, 2020). "Leptin was confirmed to enhance PAI-1 expression in breast cancer cells at both the protein and mRNA levels." (PMID 33371368, 2020). "Consistent with other findings that miR-34a significantly increased with the treatment of stattic (a small-molecule inhibitor of STAT3), we found that depletion of STAT3 markedly attenuated the leptin-induced suppression of miR-34a in breast cancer cells." (PMID 33371368, 2020). "In obese breast-cancer patients, in which adipokines such as leptin and resistin known to be related to obesity and that increase mammary tumor risk, an elevation of FABP4 correlated with tumor size and stage, and with lymph node invasion was found." (PMID 32856199, 2020). "These extremely important results add another link (leptin-Ob-R-IL-18) to the complex interaction between the tumour microenvironment and breast cancer cells that drives cancer progression." (PMID 32033341, 2020). "Compared to the control group, AMD3100 effectively decreased metastasis in leptin-treated breast cancer cells." (PMID 32836215, 2020). "Leptin levels are increased in the plasma of post-menopausal breast cancer patients, which correlated with a higher grade, advanced tumor stages and presence of distant metastasis." (PMID 33339340, 2020). "Collectively, these findings imply that adipocyte-derived leptin activated OBR to modulate PAI-1-induced breast cancer metastasis." (PMID 33371368, 2020). "In breast cancer, leptin upregulates all components of the IL-1 system (IL-1α, IL-1β, IL-1Ra and IL-1R tI) and both leptin and IL-1 together promote angiogenesis through expression of VEGF/VEGFR." (PMID 33339340, 2020).